ANG (angiogenin)
Diseases named in the same sentence as ANG in open-access papers (continued):
Sharing a sentence is not in itself a finding about the gene and the disease.
neuroblastoma (7 papers, 2012 to 2023). Neuroblastoma (NB) is the most common solid, extracranial childhood tumor. "We initially studied the time course of ANG uptake in SH—SY5Y cells, a neuroblastoma cell line, by exposing them to ANG at concentrations reported in human serum in serum free medium." (PMID 29486010, 2018). "We have previously shown that exogenous, wildtype angiogenin reduces cell death in response to the neurotoxin MPP+ in neuroblastoma cells." (PMID 23409128, 2013). "For tumour glioblastoma, we found the endogenous angiogenin localised in the nucleus and in the cytosol, while neuron-like differentiated neuroblastoma displayed a weaker angiogenin staining (according to western blotting analysis), mainly localised in cytoplasm." (PMID 31500197, 2019). "We also demonstrated that exogenous angiogenin reduced toxicity by rotenone and 1-methyl-4-phenylpyridine (MPP+) in neuroblastoma cell lines." (PMID 23409128, 2013). "To analyse the endogenous levels of ANG expression in the tested cancer cells (glioblastoma A172 and neuroblastoma SH-SY5Y) and neuronal-like cells (differentiated neuroblastoma, d-SH-SY5Y), we performed western blot analyses of protein extracts from crude cell lysates." (PMID 31500197, 2019). "Expression of angiogenin, TIMP1, and TIMP2 was specifically elevated in the PRL3-positive tumor specimens but not in PRL3-negative adjacent normal tissues, with normalized net expression of these angiogenic factors increased in neuroblastoma, leiomyosarcoma, and rhabdomyosarcoma tumors." (PMID 37674627, 2023).
portal hypertension (7 papers, 2015 to 2022). Increased blood pressure in the portal venous system. "In cirrhosis patients with complications of severe portal hypertension, circulating levels of angiogenin are derived from the injured liver." (PMID 34432848, 2021).
type 1 diabetes (7 papers, 2014 to 2025). "In young patients with type 1 diabetes, increased microangiopathic complications in adolescence were shown to be associated with significantly increased angiogenin levels, whereas maintaining tight glycemic control led to decreased levels." (PMID 39273664, 2024). "In middle-aged patients with type 1 diabetes, the angiogenin level was found to be lower than in controls." (PMID 39273664, 2024). "We showed that the angiogenin level in patients with type 1 diabetes was significantly lower compared to the control group." (PMID 37761032, 2023). "Our previous study of middle-aged patients with type 1 diabetes demonstrated significantly higher angiogenin levels in those who have already developed nephropathy when compared to those who have not." (PMID 37761032, 2023). "It is well documented that in patients with type 1 diabetes (DM1), decreased levels of angiogenin are associated with the development of overt nephropathy." (PMID 37761032, 2023). "Based on our data, abnormal angiogenesis in patients with type 1 diabetes may be related to lower angiogenin levels." (PMID 37761032, 2023). "They reported elevated levels of angiogenin in young patients with type 1 diabetes, irrespective of the degree of microvascular complications." (PMID 39273664, 2024). "A comparative analysis was conducted on the concentrations of angiogenin, VEGF (vascular endothelial growth factor), and sP-selectin, as well as sRAGE (Receptors for Advanced Glycation End Products) and AGEs (Advanced Glycation End Products) in patients with type 1 diabetes." (PMID 40564977, 2025).
type 2 diabetes (7 papers, 2017 to 2025). "Here, we sought to study the association of plasma angiogenin and major adverse cardiovascular events (MACEs) in patients with type 2 diabetes (T2D)." (PMID 38360721, 2024). "The relationship between angiogenin concentration and long-term type 2 diabetes control assessed by HbA1c levels has been studied by several researchers." (PMID 37761032, 2023). "The decreased angiogenin concentration was found in type 2 diabetes patients with hypertriglyceridemia, lower LDL-cholesterol and with HDL-cholesterol not significantly different from controls." (PMID 28918499, 2017). "A high level of plasma angiogenin is associated with an increased risk of cardiovascular events independent of traditional risk factors in patients with type 2 diabetes and preserved kidney filtration function, suggesting that plasma angiogenin may play a significant role in the pathogenesis of CVD." (PMID 38360721, 2024).
Arthritis (6 papers, 2017 to 2022). Inflammation of a joint. "ANG, or angiogenin, is most often implicated in tumor-associated angiogenesis, but has been suggested to inhibit inflammatory processes and to mediate local inflammation in arthritis." (PMID 35033099, 2022).
chronic heart failure (6 papers, 2016 to 2024). "Angiogenin has also been studied in cardiovascular diseases showing an increase in blood in chronic heart failure or in acute coronary syndrome in association with severity or prognosis." (PMID 30008694, 2018). "In addition, in a study of individuals with chronic heart failure, correlations between angiogenin levels and cardiac risk factors revealed that ANG was inversely associated with HDL cholesterol." (PMID 35205153, 2022).
Cirrhosis (6 papers, 2015 to 2021). A chronic disorder of the liver in which liver tissue becomes scarred and is partially replaced by regenerative nodules and fibrotic tissue resulting in loss of liver function. "Angiogenin level were measured in the portal and the inferior caval vein blood of patients with decompensated cirrhosis at TIPS insertion (each compartment: n = 23)." (PMID 34432848, 2021). "Since higher angiogenin concentrations were measured in the inferior caval vein than in the portal vein, the main source of angiogenin in decompensated cirrhosis may be the diseased liver." (PMID 34432848, 2021).
frontotemporal dementia (6 papers, 2010 to 2024). Frontotemporal dementia (FTD) comprises a group of neurodegenerative disorders, characterized by progressive changes in behavior, executive dysfunction and language impairment, as a result of degeneration of the medial prefrontal and frontoinsular cortices. "Frontotemporal dementia (FTD) was also reported in a large FALS pedigree with the K17I ANG mutation." (PMID 26213621, 2015). "As progranulin is functionally similar to angiogenin, and frontotemporal dementia is biologically related to ALS, a similar form of altered regulation of angiogenin may apply in ALS." (PMID 21085671, 2010). "In addition, one SALS patient with a G20G synonymous mutation, I46V mutation, and K54E mutation had frontal dementia, and one FALS patient with a K17I mutation had frontotemporal dementia (FTD), suggesting that ANG mutations may be related to cognitive impairment." (PMID 38421827, 2024).
glaucoma (6 papers, 2015 to 2025). Increased pressure in the eyeball due to obstruction of the outflow of aqueous humor. "Angiogenin is an important immune mediator in predicting primary open-angle glaucoma and is related to the process of ocular angiogenesis." (PMID 40486511, 2025). "The altered AqH levels of C3a, cortisol, and angiogenin observed in our glaucoma cohort are consistent with the findings of previous studies." (PMID 41154592, 2025). "MCP-1, IL-6, and angiogenin are important immune mediators in predicting primary open-angle glaucoma, participating in related pathological processes, though specific mechanisms require further study." (PMID 40486511, 2025). "Previous studies have observed the multi-functional benefits of angiogenin (ANG) against glaucoma." (PMID 32509448, 2020). "Two OPTN mutants and three ANG mutants were used: OPTN E50K, found in glaucoma patients; OPTN E478G; ANG K17I; ANG K40I; and ANG P112L, found in ALS patients." (PMID 28596290, 2017).
pulmonary hypertension (6 papers, 2016 to 2025). Increased pressure within the pulmonary circulation due to lung or heart disorder. "Angiogenin is also upregulated in cancer cells, mediating angiogenesis, cell proliferation, and protection from apoptosis, and is increased in breath condensates from patients with pulmonary hypertension, indicating a possible pulmonary origin in this disease." (PMID 27881557, 2017).
renal cell carcinoma (6 papers, 2017 to 2023). "seRNA-activated PI3K/AKT signaling can not only promote autophagy, but also accelerate angiogenesis in anaplastic ATC and renal cell carcinoma (RCC) through triggering GSK3β/ANG and GSK3β/AM pathway activation." (PMID 32278350, 2020).
diabetic retinopathy (5 papers, 2011 to 2020). "Results from studies assessing angiogenin levels in other ocular malignancies, namely diabetic retinopathy (DR), have been contradicting." (PMID 29096624, 2017). "Specific to diabetic retinopathy (DR), a study comparing serum and vitreous concentration of angiogenin versus VEGF showed a two-fold reduction in vitreous and serum angiogenin concentration in DR patients compared to those without DR while the reverse is seen with VEGF." (PMID 32927780, 2020).
liposarcoma (5 papers, 2012 to 2018). A usually painless malignant tumor that arises from adipose tissue. "Mutations in several genes are causative for FALS, including fused in sarcoma/translated in liposarcoma (FUS), superoxide dismutase-1 (SOD1), TAR DNA-binding protein (TARDBP), angiogenin (ANG), vesicle-associated membrane protein B (VAPB), optineurin (OPTN), and valosin-containing protein (VCP)." (PMID 23577159, 2013). "Sanger sequencing was used to screen these subjects for mutations in the coding regions of superoxide dismutase-1 (SOD1), angiogenin (ANG), fused in sarcoma/translated in liposarcoma (FUS/TLS), TAR DNA-binding protein 43 (TARDBP), and multivesicular body protein 2B (CHMP2B)." (PMID 23155438, 2012).
motor neuron diseases (5 papers, 2009 to 2021). "Among the catalogued ALS-like motor neuron diseases, mutations in SOD1 (ALS1), FUS/TLS (ALS6), VAPB (ALS8), ANG (ALS9), TARDBP (ALS10), FIG4 (ALS11) and a hexanucleotide-repeat expansion (GGGGCC) in the C9ORF72 cause adult onset neurodegenerative disorder." (PMID 22384259, 2012).
osteosarcoma (5 papers, 2011 to 2025). A usually aggressive malignant bone-forming mesenchymal neoplasm, predominantly affecting adolescents and young adults. "Maintenance of angiogenin-IgM may also be an important aspect of osteosarcoma tumorigenesis and could be linked to prognosis." (PMID 22587902, 2012). "Apatinib can inhibit tumor cell growth by blocking the VEGFR2/STAT3/Bcl-2 or Akt/GSK3β/angiogenin signaling pathways, suppressing tumor angiogenesis in osteosarcoma and anaplastic thyroid cancer, respectively." (PMID 32509141, 2020). "The advantage of this approach is that it should be possible to detect the full range of heterogenous osteosarcomas by increasing the number of angiogenin-IgM assays or altering the antigens used in the natural IgM antibodies panel." (PMID 22587902, 2012). "Correlation between the angiogenin level in the blood and the presence of metastasis, as well as the timing of metastasis, appears to have prognostic significance in osteosarcoma patients." (PMID 22587902, 2012). "SPP1, VEGFA, EMMPRIN, MIF, uPAR, Angiogenin, and Cystatin C were among the most highly expressed analytes in both patient specimens and in cell line conditioned media, demonstrating that the osteosarcoma cells themselves are a cellular source of these molecules." (PMID 39896512, 2025). "In osteosarcoma cells, ANG seems to be a main RNase responsible for tiRNA production." (PMID 35300117, 2022). "Thus, the expression of angiogenin in primary osteosarcoma correlates with an increase in the local density of blood vessels in tumor tissue, with the development of metastatic pulmonary disease and a poor prognosis." (PMID 22587902, 2012).
acute coronary syndrome (4 papers, 2013 to 2024). Signs and symptoms related to acute ischemia of the myocardium secondary to coronary artery disease. "Moreover, high angiogenin levels have been linked with peripheral occlusive arterial disease and acute coronary syndrome." (PMID 33574979, 2021). "Tello-Montoliu and colleagues also showed that in patients (N = 440) with acute coronary syndrome (ACS), a high level of angiogenin is associated with adverse events at the six-month follow-up." (PMID 38360721, 2024).
cervical cancer (4 papers, 2017 to 2025). A primary or metastatic malignant neoplasm involving the cervix. "The CFS of Probio87 significantly downregulated key pro-angiogenic factors—VEGF, ANG-2, and Angiogenin—across all three cervical cancer cell lines compared to the vehicle control." (PMID 40806138, 2025). "In addition to its cytotoxic effects, Probio87 CFS significantly downregulated key pro-angiogenic factors—VEGF, ANG-2, and Angiogenin—in all three cervical cancer cell lines." (PMID 40806138, 2025). "A question of interest is that of the role of mediating mechanisms in cervical cancer, which may be similar to those seen in inflammation, with tumor conditions potentially leading to Tie-1 extracellular cleavage and activating the ANG/Tie-2 pathway, resulting in tumor angiogenesis." (PMID 34975347, 2021).
hepatocellular carcinoma (4 papers, 2022 to 2024). A malignant tumor that arises from hepatocytes. "Angiogenin in hepatocellular carcinoma plays a crucial role in tumor vasculature construction; however, its role in normal liver physiology has been challenging to elucidate." (PMID 38715085, 2024). "A study on hepatocellular carcinoma indicated that Met decreased only angiogenin expression out of 20 angiogenesis-related proteins." (PMID 35656067, 2022).
inflammatory bowel disease (4 papers, 2014 to 2023). A spectrum of small and large bowel inflammatory diseases of unknown etiology. "Recent studies have demonstrated that human ANG may act as a diagnostic biomarker for several diseases such as cardiovascular diseases, cancer, and inflammatory bowel diseases." (PMID 38020881, 2023). "Serum ANG was found to be increased in patients with inflammatory bowel disease, and ANG mRNA expression was shown to be elevated by TNF-α and IL-1β." (PMID 24860242, 2014). "In animal models also, vitamin D showed a decreased expression of ANG protein resulting in the higher invasion of colon epithelium by bacteria suggesting a role of vitamin D in the downregulation of tissue inflammation in inflammatory bowel diseases." (PMID 35205153, 2022). "Regarding ANG levels in inflammation-related diseases, 2 studies reported that serum ANG levels were increased in patients with inflammatory bowel disease (IBD), that is, patients with ulcerative colitis (UC) and Crohn's disease (CD), compared with those in healthy controls." (PMID 29736193, 2018).
acute myeloid leukemia (3 papers, 2018 to 2021). Acute myeloid leukemia (AML) is a group of neoplasms arising from precursor cells committed to the myeloid cell-line differentiation. "Elevated levels of ANG have been detected in a number of cancer cell lines and tumor tissues including hematopoietic, leukemic cells and the plasma of Acute Myeloid Leukemia (AML) and advanced myelodysplastic syndromes (MDS) patients." (PMID 33525475, 2021). "For instance, high concentrations of serum hRNase5/ANG have been observed in patients who suffer from various cancer types, such as colorectal cancer, lung cancer, and acute myelogenous leukemia, in which EGFR has been well studied to be a therapeutic target in clinical practice." (PMID 30449278, 2018).
autoimmune disease (3 papers, 2014 to 2023). A disorder resulting from loss of function or tissue destruction of an organ or multiple organs, arising from humoral or cellular immune responses of the individual to their own tissue constituents. "Angiogenin (ANG) is the multifunctional factor that plays role in angiogenesis but also in autoimmune diseases as anti-inflammatory agent." (PMID 32190059, 2020). "Angiogenin (ANG) is reportedly multifunctional, with roles in angiogenesis and autoimmune diseases." (PMID 24860242, 2014).
bladder tumor (3 papers, 2014 to 2019). "Our findings pave the way to advance our understanding of human bladder tumor biology and confirm ANG as a potential biomarker and as a target for therapeutic intervention." (PMID 27317771, 2016). "In summary, we demonstrate that ANG is overexpressed in approximately 45% of bladder tumors." (PMID 27317771, 2016). "Previously, we reported a novel interplay between angiogenin (ANG), a potent mediator of angiogenesis, and matrix metalloproteinase-2 (MMP2) in human bladder tumors." (PMID 27317771, 2016).
Cerebral ischemia (3 papers, 2013 to 2019). Restriction of arterial blood supply to the brain associated with insufficient oxygenation to support the metabolic requirements of the tissue. "Further, two rehabilitation models in mice after cerebral ischemia (task-specific based exercise or physical exercise) are used, where brain and circulating angiogenin determinations together with EPCs cultures are analyzed." (PMID 30008694, 2018). "Our hypothesis is that angiogenin and EPCs are modulated during rehabilitation after cerebral ischemia serving as biomarkers of functional/motor outcome related to their participation in plasticity mechanisms during neurorepair." (PMID 30008694, 2018).
colon adenocarcinoma (3 papers, 2007 to 2022). "Angiogenin (ANG), a secreted 14-kDa protein, was isolated originally from the conditioned medium of human colon adenocarcinoma HT-29 cells based on its angiogenic activity." (PMID 35463945, 2022). "Angiogenin (ANG) is a 14-kDa angiogenic protein originally isolated from the conditioned medium of HT-29 human colon adenocarcinoma cells based solely on its capacity to induce angiogenesis." (PMID 23977052, 2013). "Angiogenin (ANG), a potent in vivo inducer of angiogenesis, was first isolated in a systematic search for angiogenic factors secreted by human HT-29 colon adenocarcinoma cells." (PMID 17883850, 2007).
depression (3 papers, 2020 to 2022). "In the In a mouse model of depression, repeated Arctigenin treatment shows antidepressant- and anxiolytic-like effects via promoting the expressions of angiogenin (ANG), thrombopoietin (TPO), and vascular endothelial growth factor (VEGF)." (PMID 33574759, 2020).
gastric cancer (3 papers, 2010 to 2023). A primary or metastatic malignant neoplasm involving the stomach. "Our data suggest that ANG2 and the ANG/TIE pathway comprise a potential target for therapy for gastric cancer patients." (PMID 35740619, 2022). "We found that coculture of gastric cancer cells with H. pylori induces expression of mRNAs encoding IL-8, VEGF-A, angiogenin, urokinase-type plasminogen activator, and MMP-9 by gastric cancer cells." (PMID 20369064, 2010). "Moreover, its level of expression directly correlates with tumor stage, suggesting that the ANG–TIE pathway has a potential role in gastric cancer spread and its adverse clinical outcomes." (PMID 35740619, 2022).
leukemia (3 papers, 2011 to 2019). A malignant (clonal) hematologic disorder, involving hematopoietic stem cells and characterized by the presence of primitive or atypical myeloid or lymphoid cells in the bone marrow and the blood. "Angiogenin (ANG) promotes angiogenesis and tumor growth and was found to be overexpressed in leukemia." (PMID 31064135, 2019). "Our ex vivo data revealed that six of seven leukemia patients responded to the CD64-directed hCFP and its cytotoxic efficacy was similar to that of hCFPs based on granzymes or angiogenin." (PMID 27564103, 2016).
lymphoma (3 papers, 2010 to 2023). A malignant (clonal) proliferation of B- lymphocytes or T- lymphocytes which involves the lymph nodes, bone marrow and/or extranodal sites. "Of interest, the ability of MSC cultures of secreting high levels of angiogenic cytokines, such as VEGF, IL-8, angiogenin and CCL2, was significantly (p<0.01) enhanced by the concomitant presence of lymphoma cells." (PMID 20585401, 2010).